KRAS (KRas proto-oncogene, GTPase)
Diseases named in the same sentence as KRAS in open-access papers (continued):
Sharing a sentence is not in itself a finding about the gene and the disease.
colorectal cancer (continued). "The clinical applicability of these assays was assessed by analyzing 100 colorectal cancer samples, for which KRAS mutation status has been evaluated by the commercially available TheraScreen® KRAS mutation kit." (PMID 23173730, 2012). "Further, in a recent study of 143 Korean patients with metastatic or recurrent colorectal cancer, lung metastasis was more frequently the initial metastatic site in patients with the KRAS mutations." (PMID 23202889, 2012). "Model VARI-LTM-041 colorectal cancer contained three mutations (KRAS and two PIK3CA mutations) that were also present in the matching tumor." (PMID 22709571, 2012). "To further assess the association between KRAS mutations and different clinical features in patients with colorectal cancer, we fitted univariate and multivariate logistic regression models." (PMID 22675430, 2012). "Among the colorectal carcinoma specimens, we detected a KRAS codon 12 or 13 mutation in half of the samples (10/20, 50%), but a BRAF codon 600 mutation only in one sample (1/20, 5%)." (PMID 22808230, 2012). "Prevalence of KRAS mutations in our series is consistent with data from literature, indicating that such an alteration can be found in 30-40% of colorectal carcinomas." (PMID 22931052, 2012). "In these polyps and in colorectal carcinomas, there is significant overexpression of the protein in KRAS-mutated lesions compared to both wild-type and BRAF-mutated controls." (PMID 22808230, 2012). "Somatic KRas mutations are found in many cancers, including 30%–40% of colorectal cancers, and are an early event in carcinogenesis." (PMID 21403829, 2011). "In contrast to colorectal cancer, the prevalence of KRAS mutations in gastric cancer is low and consequently, a relationship between KRAS mutations and therapy response is difficult to establish." (PMID 22152101, 2011). "In tumor types with more than 10 patients tested, KRAS mutations were most frequent in colorectal cancer, in 49 (51%) of 97 tested patients." (PMID 21829508, 2011). "For non-small-cell lung cancer, the population approved for gefitinib is defined by the presence of specific EGFR mutations, whereas for colorectal cancer, patients with KRAS mutations are excluded from treatment by cetuximab." (PMID 21966417, 2011). "In colorectal cancer, only KRAS mutation was identified as an independent indicator for poor OS from time of diagnosis and metastasis (HR: 13.56, 95% CI 1.61–113.88, p = 0.016 and HR: 5.46, 95% CI 1.07–27.89, p = 0.04 respectively)." (PMID 22039425, 2011). "Pyrosequencing offers cost-effective quantitative detection of sequence variants and was previously shown to enable sensitive KRAS mutation detection in colorectal cancer." (PMID 21573178, 2011). "Of particular interest is a KRAS gene mutation occurring in codon 12 (G12D) which is a hot spot mutation commonly identified in colorectal cancer." (PMID 21738606, 2011). "Of note, KRAS-G12D has a high prevalence (35%); this cancer driver mutation is present in 40% of colorectal cancers and is associated with anti-EGFR therapy resistance." (PMID 22185227, 2011). "This cell line also harbors an activating KRAS G12V mutation, which is associated with resistance of colorectal cancers to the EGFR-directed therapy cetuximab." (PMID 21666749, 2011). "Mutations in the KRAS gene occur early in the development of many cancers and are found in more than 90% of pancreatic adenocarcinomas, 40% of colorectal cancers (CRC) and 33% of non-small cell lung carcinomas (NSCLC)." (PMID 21943394, 2011). "Although studies in colorectal carcinoma have shown that somatic KRAS mutation is associated with resistance to cetuximab, the present study has shown KRAS mutations to be rare in cervical carcinomas." (PMID 21730982, 2011).
colorectal cancer (continued). "Among the most harmful of all genetic abnormalities that appear in colorectal cancer (CRC) development are mutations of KRAS and its downstream effector BRAF as they result in abnormal extracellular signal-related kinase (ERK) signaling." (PMID 20942929, 2010). "It has been reported that primary colorectal cancers, which showed KRAS or BRAF mutations, also frequently showed RASSF2 methylation, and inactivation of RASSF2 enhanced KRAS-induced oncogenic transformation." (PMID 20920251, 2010). "To elucidate regulatory principles of pathway-triggered gene transcription, we firstly identified common clusters of target genes sensitive to MEK inhibition in three colorectal cancer cell lines carrying KRAS or BRAF mutations." (PMID 21170361, 2010). "It was shown that mutations in APC and KRAS occur in approximately 80% and 50%, respectively, of sporadic colorectal cancer." (PMID 20298593, 2010). "Oncogenic mutations in KRAS or BRAF occur frequently in colorectal cancer and aberrant signaling through the ERK pathway has been correlated with both initiation and progression of CRC." (PMID 20942929, 2010). "KRAS mutational status of stage IV colorectal cancer is a predictive biomarker for anti-EGFR treatment." (PMID 20808308, 2010). "While gastric cancer is sharing many phenotypic and molecular genetic changes with colorectal cancer, recent molecular studies in gastric cancer have mostly found a lower incidence of KRAS mutation than in colorectal cancer." (PMID 20977739, 2010). "We next validated the COLD-PCR melting curve assay using FFPE colorectal cancer specimens with distinct characterized KRAS mutations." (PMID 21110880, 2010). "Both mutational inactivation of the adenomatous polyposis coli (APC) tumor suppressor gene and activation of the KRAS oncogene are implicated in the pathogenesis of colorectal cancer." (PMID 20298593, 2010). "In this retrospective study, high-resolution melting analysis (HRMA) was validated and implemented for screening of 164 colorectal cancer (CRC) patients to detect KRAS hot-spot mutations and to evaluate its prognostic value." (PMID 20959826, 2010). "NSCLC KRAS mutations mainly occur as transversions (78.6%) and KRAS mutations of colorectal carcinomas are evenly distributed as transition and transversion." (PMID 21197450, 2010). "For example, lung and colorectal cancers that harbor mutations in the KRAS oncogene are unresponsive to treatment with anti-EGFR agents, and inactivating PTEN mutations (or protein loss) in glioblastomas predict resistance to erlotinib." (PMID 19924296, 2009). "KRAS mutations represent key alterations in colorectal cancer development and lead to constitutive EGFR signaling." (PMID 19832985, 2009). "APC gene mutations, as well as KRAS mutations, are recognized as early events in colorectal cancer development." (PMID 19832985, 2009). "Based on our results and previous observations, concurrent KRAS mutations seem to occur in about 3% of colorectal cancers." (PMID 19832985, 2009). "Mutations in the KRAS oncogene typically occur already in the late adenoma stage and have since long been recognized as a key event in colorectal cancer development." (PMID 19832985, 2009). "The observation of coexisting KRAS mutations in a small number of colorectal cancers, however, suggests that some tumors benefit from repeated targeting of the same pathway." (PMID 19832985, 2009). "We used a real-time PCR based method to determine KRAS mutations in 136 colorectal cancers with mutations identified in 53 (39%) tumors." (PMID 19832985, 2009). "Since EGFR inhibition represents a therapeutic strategy in advanced colorectal cancer, KRAS mutation analysis has quickly been introduced as a treatment-predictive test." (PMID 19832985, 2009). "Established examples include KRAS mutations in non-small cell lung cancer (23%) and colorectal cancer (38%) that confer resistance to erlotinib, gefitinib (lung) or cetuximab (colorectal)." (PMID 19924296, 2009).
colorectal cancer (continued). "KRAS mutations occur most frequently in 30–40% of all colorectal cancers and BRAF mutations are present at a frequency of 5–22%, in which the constitutively activated BRAFV600E variant accounts for ∼90% of all the BRAF mutations." (PMID 20027224, 2009). "The mutual exclusivity of BRAF and KRAS mutations in our ovarian carcinoma is consistent with previous findings in ovarian carcinoma, melanoma, and colorectal carcinoma." (PMID 19638206, 2009). "Ten of the 50 (20%) MSI and 21 of the 53 (39.6%) MSS colorectal carcinomas exhibited KRAS mutations." (PMID 18782444, 2008). "A prominent example is the mutually exclusive occurrence of the BRAF hotspot mutation (V600E) and KRAS mutations in colorectal cancer." (PMID 15784156, 2005). "KRAS mutations at codon 12 induce profound metabolic changes in colorectal cancer cells." (PMID 41266617, 2026). "KRAS mutations are present in approximately 45% of colorectal cancer (CRC) patients." (PMID 41362735, 2026). "Based on the observed inhibition of metastatic KRAS-mutated CRC tumor growth following LS-1-2 treatment, we investigated whether LS-1-2 could directly prevent liver metastasis in KRAS-mutated colorectal cancer." (PMID 41362735, 2026). "Taken together, these findings suggest that extracellular PrPC supports RAS-AKT signaling, proliferation, and tumor-associated angiogenesis in KRAS-mutant colorectal cancer, and that PrPC neutralization additively enhances 5-fluorouracil activity in KRAS-mutant models." (PMID 41683587, 2026). "In an evaluation of 45 clinical tumor RNA specimens spanning pancreatic, cholangiocarcinoma, and colorectal cancers, the assay correctly classified mutation status with full concordance for KRAS G12D, IDH1 R132C and BRAF V600E, with a subset of positive cases corroborated by orthogonal RT-ddPCR." (PMID 42080370, 2026). "Remarkably, elevated expression levels of UBE2V1/2 correlate with improved survival rates in human colorectal cancer patients harboring oncogenic KRAS mutations, indicating that their upregulation could represent a promising therapeutic strategy." (PMID 41879050, 2026). "Interestingly, this mutation has been associated with a more favorable OS compared to other KRAS variants in colorectal cancer." (PMID 40927517, 2025). "The mechanisms underlying the enhanced radioresistance in KRAS-mutated tumours have been studied using colorectal cancer cell lines, which revealed that mutated KRAS isoforms activate EGFR and H-Ras, resulting in enhanced cellular radioresistance through PI3K/AKT signalling." (PMID 41226343, 2025). "Kirsten rat sarcoma viral oncogene homolog (KRAS) mutations are prevalent in colorectal cancer." (PMID 40519270, 2025). "MRTX1133 obtained clearance as an investigational new drug (IND) by the FDA in October 2021 for a phase I/II clinical trial (NCT05737706), targeting patients with advanced solid tumors (PDAC, NSCLC, colorectal cancer, and others) harboring the KRAS G12D mutation." (PMID 40597785, 2025). "KRAS mutations are detected in 40–50% of patients with colorectal cancer." (PMID 40142219, 2025). "In accordance with prior evidence suggesting a functional association between KCNN4 and KRAS signaling in colorectal cancer, our analysis revealed that KCNN4 expression is significantly elevated in KRAS‐mutant PDAC samples compared to wild‐type (Wilcoxon p = 3.5 × 10−16)." (PMID 40952239, 2025). "Furthermore, MRTX1133 suppresses progression of KRAS G12D-mutated colorectal cancer by inducing ferroptosis via the METTL14/LINC02159/FOXC2 axis." (PMID 40746552, 2025). "KRAS mutation in colorectal cancer may be associated with aggressive tumor behavior through increased invasiveness and higher rates of lung metastases." (PMID 40549756, 2025). "Additionally, it was stated that E. angustifolia fruit extract prevented colorectal cancer in Drosophila melanogaster with a KRAS (Kirsten Rat Sarcoma viral oncogene homolog) gene mutation." (PMID 40621190, 2025).
colorectal cancer (continued). "Additionally, the absence of prognostic significance in TCGA (non-ICI-treated cohort) underscores its context-specific predictive role, akin to KRAS mutations in colorectal cancer." (PMID 40873541, 2025). "KRAS mutations occur in approximately 40% of colorectal cancer (CRC) cases." (PMID 40361439, 2025). "In colorectal cancer, the same database reports 40% of KRAS and 65% of APC variants." (PMID 40916582, 2025). "However, consistent with other findings, POLE-mutated colorectal cancers were significantly associated with younger age, right-sided colon location, poor histological grade, early stage, and KRAS/NRAS/BRAF wild-type status." (PMID 40310397, 2025). "KRAS mutations, while common in colorectal cancer overall, remain prevalent also in EOCRC, though their distribution may differ across cohorts." (PMID 41463160, 2025). "To support this review, we describe our methodology for literature selection, including databases searched (PubMed, Scopus, and ClinicalTrials.gov), keywords used (e.g., “RAS mutation”, “colorectal cancer”, “KRAS”, and “targeted therapy”), and the timeframe (January 2010 to March 2025)." (PMID 40731832, 2025). "Furthermore, schistosome egg deposition in colorectal cancer is linked to a higher rate of the KRAS G12D mutation, which is also a key driver mutation in pancreatic cancer." (PMID 41490744, 2025). "Furthermore, the mouse model used in this study was tailored to APC and KRAS mutations in colorectal cancer, limiting the applicability of the findings to other genetic alterations or tumor types." (PMID 41285904, 2025). "KRAS mutations play a pivotal role in the multistep progression of colorectal cancer." (PMID 40361439, 2025). "Moreover, KRAS mutations have been linked to poor outcomes in non-small cell lung cancer and in colorectal cancer." (PMID 39996841, 2025). "In targeted therapy, studies on KRAS G12C-mutated colorectal cancer have demonstrated significant efficacy of Sotorasib (AMG 510) as a monotherapy, while combining it with anti-EGFR agents like Panitumumab is being explored to address resistance and improve outcomes." (PMID 41361128, 2025). "The KRAS mutation has always generated considerable interest regarding the potential to exploit its positivity, as it is one of the most important oncogenic mutations in colorectal cancer (CRC)." (PMID 40141164, 2025). "The presence of KRAS mutations in colorectal cancer carries significant clinical implications." (PMID 39941797, 2025). "KRAS G12C inhibitors thus far have only been approved for use as a monotherapy in non-small cell lung cancer and as a combination therapy in colorectal cancer, partially because of the rarity of the G12C allele and partially because of a lack of drug sensitivity in certain tumor types." (PMID 40779492, 2025). "KRAS mutations in colorectal cancer are commonly associated with a MSS phenotype and poor response to single−agent immune checkpoint inhibitors; notably, in the KEYNOTE−177 trial, MSI−H CRC patients harboring KRAS or NRAS mutations did not benefit from ICI monotherapy." (PMID 40547026, 2025). "Because KRAS mutations are involved in resistance to cetuximab in colorectal carcinoma, we next examined whether resistance to cetuximab and cisplatin, key anticancer agents for HNCs, is associated with HRAS." (PMID 40243851, 2025).
colorectal cancer (continued). "Mutations in KRAS related to colorectal cancer result in gain-of-function with a decrease in GTPase activity of RAS and hence an increase in GTP-bound RAS and consequent persistent activation of the signaling pathways responsible for cell proliferation and carcinogenic cellular transformation." (PMID 38891084, 2024). "Clinical studies have indicated that a combination of anti‐EGFR targeted therapy and KRAS c.34G>T (p.G12C) inhibitor could be an effective treatment strategy in KRAS c.34G>T (p.G12C)‐mutated colorectal cancer." (PMID 39039804, 2024). "Furthermore, one study concluded that a KRAS mutation is associated with suppressed Th1/cytotoxic immunity in colorectal cancer, which provided a basis for interpreting the association between KRAS mutations and colorectal adenosquamous carcinoma." (PMID 38229035, 2024). "Mutations in KRAS drive oncogenesis, especially in pancreatic, lung, and colorectal cancers (CRC)." (PMID 39179604, 2024). "KRAS mutations are present in approximately 40% of colorectal cancer (CRC) patients." (PMID 38481800, 2024). "In colorectal cancer, the mutation of KRAS or BRAF genes could increase the expression level of glucose transporter‐1 (GLUT1) and enhance glycolysis." (PMID 38613347, 2024). "In addition, the detection of EpCAM, CK19, CK20, and MUC2 and the presence of mutations in KRAS in CTCs from peripheral blood samples can detect colorectal cancer." (PMID 40026568, 2024). "One example is KRAS, an oncogene mutated in 40% of colorectal cancers." (PMID 39010058, 2024). "In addition, we showed that, among BRAF‐wild‐type cases, both KRAS c.34G>T (p.G12C) mutation and KRAS mutations other than c.34G>T were associated with higher colorectal cancer‐specific mortality compared with KRAS‐wild‐type cases." (PMID 39039804, 2024). "Can CT-based radiomics signature predict KRAS/NRAS/BRAF mutations in colorectal cancer?" (PMID 38608072, 2024). "This suggests that Lu/BCAM may play a significant role in the metastasis of KRAS-mutated colorectal cancer cells and could potentially serve as a therapeutic target for patients with KRAS mutations in colorectal cancer." (PMID 39000374, 2024). "The KRAS gene is mutated in approximately 45% of colorectal cancer patients." (PMID 39057088, 2024). "It has been indicated that hypermethylation of the MGMT promoter may contribute to the development of colorectal cancer by promoting KRAS mutations through the inactivation of a DNA repair gene." (PMID 39218931, 2024). "Therefore in the following study we used the tumor cell lines expressing the most common KRAS origin in colorectal cancer as our in-depth study, and also included more KRAS mutated types of colorectal cancer cell lines." (PMID 38216883, 2024). "KRAS mutations are associated with poor prognosis in colorectal cancer (CRC)." (PMID 39523457, 2024). "In this study, we aimed to evaluate the expression of SEMA7A, SEMA4D, ADAM8, and ADAMTS10 in colorectal cancer (CRC) in relation to the mutational landscape of KRAS, NRAS, BRAF, PIK3CA, and AKT genes, microsatellite instability (MSI) status, and clinicopathological features." (PMID 39329961, 2024). "KRAS is an oncogene, mutated in approximately 35–45% of colorectal cancers." (PMID 38674412, 2024). "Our study highlights the therapeutic uses of carbamazepine on cancer, and we propose that carbamazepine in conjunction with other chemotherapies may prove useful in targeting KRAS-mutated colorectal cancer." (PMID 38446332, 2024).